DEFA3 (defensin alpha 3)
Description:
Effector molecule of the innate immune system that acts via antibiotic-like properties against a broad array of infectious agents including bacteria, fungi, and viruses. Possesses the ability to neutralize bacterial toxins such as B.anthracis lethal factor, Clostridium difficile cytotoxin B as well as leukocidin produced by Staphylococcus aureus. Also blocks herpes simplex virus infection by interacting with envelope glycoprotein B and thus preventing its binding to heparan sulfate, the receptor for attachment.
Synonyms: HP-3; HP3; DEF3; HNP-3; HNP3
Tractability: Antibody: UniProt places it where antibodies can reach, with high confidence; its Gene Ontology location is reachable by antibodies, with high confidence; UniProt predicts a signal peptide or a membrane-spanning region.
Gene: Protein-coding gene on chromosome 8 (7,015,869 to 7,018,359, reverse strand). Ensembl gene ENSG00000239839.
Subcellular location: Secreted
Pathways (Reactome):
Immune System: Alpha-defensins; Defensins
Gene Ontology:
Molecular function: protein homodimerization activity; pore-forming activity
Biological process: antibacterial humoral response; antimicrobial humoral immune response mediated by antimicrobial peptide; defense response to Gram-positive bacterium; estrogen receptor signaling pathway; innate immune response in mucosa; killing of cells of another organism; defense response to Gram-negative bacterium; disruption of plasma membrane integrity in another organism; innate immune response; defense response
Cellular component: extracellular exosome; extracellular region; azurophil granule lumen; Golgi lumen
Genetic constraint (gnomAD): Loss-of-function variants: 0 observed, 4.04 expected, observed/expected ratio (o/e) 0, 90% interval 0 to 0.74. That is too few expected variants to judge how well the gene tolerates losing a copy. Missense variants: 7 observed, 30.45 expected, observed/expected ratio (o/e) 0.23, 90% interval 0.13 to 0.43. Synonymous variants: 2 observed, 8.04 expected, observed/expected ratio (o/e) 0.25, 90% interval 0.1 to 0.78.
Homologues: Orthologues: chimpanzee DEFA1 (95% identical), macaque DEFA1B (83% identical), rabbit MCP-1 (44% identical), rat Defa5 (36% identical), mouse Defa2 (35% identical), mouse Defa20 (35% identical), mouse Defa32 (35% identical), mouse Defa33 (35% identical), mouse Defa34 (35% identical), mouse Defa5 (35% identical), mouse Defa17 (34% identical), mouse Defa21 (34% identical), and 30 more. Paralogues in human: DEFA1 (99% identical), DEFA1B (99% identical), DEFA6 (49% identical), DEFA5 (48% identical), DEFA4 (46% identical).
Diseases named in the same sentence as DEFA3 in open-access papers:
DEFA3 is named in the same sentence as 49 diseases in open-access papers, as found by Europe PMC text mining. Sharing a sentence is not in itself a finding about the gene and the disease. The quoted sentences say what the papers report.
COVID-19 (11 papers, 2021 to 2025). A disease caused by infection with severe acute respiratory syndrome coronavirus 2. "In this study, we have observed significantly elevated levels of α-defensins (DEFA1 and DEFA3) in COVID-19 and GBS." (PMID 38115996, 2023). "The increase in the levels of histone H4, MPO, LCN2, PGLYRP1and DEFA3 detected in our proteomic analysis strongly support the observation that excessive NET formation occurs in severe COVID-19 patients." (PMID 36348270, 2022). "Single cell RNA sequencing analyses showed the increased presence of dysfunctional neutrophils expressing S100A8, S100A9, DEFA3 and DEFA4 genes in the PBMCs of severe COVID-19 patients suggesting association of the phenotypic alterations in neutrophils with disease severity." (PMID 34746027, 2021). "When separating the three datasets, we could see that three months after the acute infection, the long COVID-19 patients sample had a prominent immature neutrophil population in their PBMCs, which had expressed markers such as CD24 and DEFA3, and this population had almost diminished after 2 years." (PMID 38248331, 2024). "Among these alterations, we confirmed by ELISA that higher levels of the neutrophil granule proteins DEFA3 and LCN2 are present in COVID-19 patients requiring ICU admission when compared to non-ICU and healthy donors." (PMID 36348270, 2022). "ELISA of an independent group of patients have confirmed that MPO, LCN2 and DEFA3 are increased in COVID-19 ICU/F patients when compared to HDand observed that LCN2 and DEFA3 can discriminate ICU/F from non-ICU COVID-19 patients." (PMID 36348270, 2022). "Conversely, DEFA3 and LCN2/NGAL shows significant differences between COVID-19 ICU and non-ICU patients confirming that neutrophil activation could be a hallmark of COVID-19 severity." (PMID 36348270, 2022).
Sepsis (8 papers, 2018 to 2023). Sepsis is defined as life-threatening organ dysfunction caused by a dysregulated host response to infection. "In another study, the same group also observed that DEFA1/DEFA3 participate in host immune response to sepsis and its higher copy number variation was significantly associated with sepsis risk." (PMID 35345767, 2022). "A genetic association study found that increased copy number of the HNP-encoding gene DEFA1/DEFA3 is a risk factor for organ dysfunction during sepsis development." (PMID 30718392, 2019). "We show that transgenic mice with high copy number of DEFA1/DEFA3 [encoding human neutrophil peptides 1–3 (HNP1–3)] suffer from more severe sepsis because of more extensive endothelial barrier dysfunction and endothelial cell pyroptosis." (PMID 30718392, 2019). "Thus, combined with our previous case-control genetic association study, these human and transgenic mouse model-based findings indicate that HCN of DEFA1/DEFA3 is a causative genetic factor for sepsis development." (PMID 30718392, 2019). "However, despite the implication of HNP1–3 in sepsis outcomes, little is known about the functional role of DEFA1/DEFA3 variants in the pathophysiology of sepsis." (PMID 30718392, 2019). "Interestingly, higher copy numbers of DEFA1/DEFA3 CNV have been associated with a risk for severe sepsis." (PMID 29950924, 2018). "Using a transgenic mouse model, we further confirmed that mice with high copy numbers of DEFA1/DEFA3 suffer from more severe pathophysiologic changes during sepsis progression." (PMID 35935811, 2022). "A study showed that the overexpression of HNP1-3 (DEFA1/DEFA3) remarkably damaged the clinical characteristics of sepsis, making patients in China displayed a high gene copy number of DEFA1/DEFA3 means more easily affected by severe sepsis." (PMID 36776394, 2022). "Human and mouse studies have shown that increased copy numbers of DEFA1/DEFA3 worsen sepsis outcomes." (PMID 35935811, 2022). "Our previous genetic association study found that DEFA1/DEFA3 (the genes that encode HNP1-3) copy number variations are genetic risk factors for sepsis, and that individuals with high copy numbers of DEFA1/DEFA3 are more susceptible to sepsis." (PMID 35935811, 2022). "To determine how the increased dose of DEFA1/DEFA3 led to endothelial cell pyroptosis during sepsis, we first examined the protein level of HNP1–3 in vivo after septic challenge." (PMID 30718392, 2019). "Taken together, these data show that endothelial barrier dysfunction contributes to sepsis deterioration in mice carrying HCN of DEFA1/DEFA3 genes." (PMID 30718392, 2019). "We thus demonstrate that DEFA1/DEFA3 copy number variation strongly modulates sepsis development in vivo and explore a paradigm for the precision treatment of sepsis tailored by individual genetic information." (PMID 30718392, 2019). "Transgenic mice models were engineered to produce a high gene copy number of DEFA-1/DEFA-3, which manipulated the outcome of sepsis progression." (PMID 31877866, 2019). "To investigate the potential role of genetic CNVs of DEFA1/DEFA3 in sepsis development in vivo, we constructed a transgenic mouse model that expresses human DEFA1/DEFA3 under its endogenous regulatory sequences to recapitulate human defensin pathophysiology." (PMID 30718392, 2019). "In both assays, compared with WT mice and the mice with LCN, those carrying HCN of DEFA1/DEFA3 had significantly increased extravasation of dyes in the vessel beds of lungs, kidneys, and mesentery at 72 h after the initiation of sepsis." (PMID 30718392, 2019). "Based on these findings, we engineered a monoclonal antibody against HNP-1 to block the interaction with P2X7 and found that the blocking antibody protected mice carrying high copy number of DEFA1/DEFA3 from lethal sepsis." (PMID 30718392, 2019).
Sepsis (continued). "To test the effect of increased dosage of DEFA1/DEFA3 genes in another clinically relevant murine model of sepsis, we used intraperitoneal administration of Escherichia coli." (PMID 30718392, 2019). "Here, we present experimental evidence for the impact of DEFA1/DEFA3 CNVs on sepsis development and explore the mechanism by which HNP1–3 promotes endothelial barrier dysfunction and endothelial cell pyroptosis." (PMID 30718392, 2019). "Experiments to analyze the specific roles of DEFA1/DEFA3 CNVs in sepsis are challenging because mice naturally lack neutrophil defensins." (PMID 30718392, 2019). "In the present study, mice engineered to have HCN of DEFA1/DEFA3 genes showed more severe organ damage and a worse outcome after sepsis challenge, indicating a genotype-restricted function in phenotype development." (PMID 30718392, 2019). "Recently, experimental evidence has highlighted the genetic association between the clinical phenotype of sepsis and DEFA-1/DEFA-3 copy number." (PMID 31877866, 2019). "We asked whether endothelial dysfunction played an important role in worse sepsis outcomes of mice with HCN of DEFA1/DEFA3 genes." (PMID 30718392, 2019). "Thus, the blocking antibody against the interaction between HNP-1 and P2X7 can protect mice with HCN of DEFA1/DEFA3 from lethal sepsis." (PMID 30718392, 2019). "Thus, using the DEFA1/DEFA3 transgenic mouse models, these findings suggest a causative link between DEFA1/DEFA3 CNVs and sepsis outcome." (PMID 30718392, 2019). "Notably, at 72 h after sepsis development, the mice carrying HCN of DEFA1/DEFA3 showed a marked loss of CD31+ endothelial cells in microvessels from lung, kidney, and mesentery, which presumably resulted from lethal injury of the endothelial cells." (PMID 30718392, 2019). "Interestingly, they reported that transgenic mice carrying more copies of the DEFA1/DEFA3 suffer from more severe sepsis and mortality than those with low copy numbers of DEFA1/DEFA3 and wild-type mice, which is caused by broader endothelial barrier dysfunction and EC pyroptosis." (PMID 32948742, 2020). "Therefore, we questioned whether increased DEFA1/DEFA3 gene dosage could affect the host inflammatory response and bacterial clearance during sepsis." (PMID 30718392, 2019). "Examples of genes related to this pathway that were differentially expressed in our sepsis samples include DEFA1, DEFA3, S100A8, S100A9 and RNASE6." (PMID 37731199, 2023). "To confirm the contribution of cell-specific expression of the transgenes to the observed effect on sepsis, we generated BM-chimeric mice by reconstituting lethally irradiated WT mice with syngeneic BM with LCN of DEFA1/DEFA3, HCN of DEFA1/DEFA3, or WT." (PMID 30718392, 2019). "To examine the therapeutic potential of the blocking antibody in established sepsis, we treated mice with HCN of DEFA1/DEFA3 at an initial time of 12 h post-CLP and thereafter at 36 and 60 h." (PMID 30718392, 2019). "Taken together, these findings demonstrate that after sepsis onset, vascular endothelia are excessively activated and dysfunctional in mice carrying HCN of DEFA1/DEFA3." (PMID 30718392, 2019). "In DEFA1/DEFA3 transgenic mice, increased gene copy numbers of DEFA1/DEFA3 worsen sepsis by inducing endothelial pyroptosis and vascular permeability in a canonical Nod-like receptor family pyrin domain containing 3 (NLRP3)/caspase-1 inflammasome dependent manner." (PMID 35935811, 2022). "In this study, the protein levels of vascular cell adhesion molecule 1 (VCAM1) and intercellular adhesion molecule 1 (ICAM1) in the lung tissue of DEFA1/DEFA3-HCN mice were significantly higher than those of DEFA1/DEFA3-LCN mice and WT mice 24 hours after the onset of disease septicemia." (PMID 36776394, 2022).
Sepsis (continued). "These dose-dependent effects of HNP-1 on endothelial cell viability were closely consistent with in vivo findings showing that mice carrying HCN of DEFA1/DEFA3 had more pyroptotic endothelial cells than those with LCN of DEFA1/DEFA3 and WT controls during sepsis development." (PMID 30718392, 2019). "Thus, we employed transgenic mice expressing HNP1–3 to explore the nonredundant functions of DEFA1/DEFA3 genes in sepsis." (PMID 30718392, 2019). "However, depletion of macrophage/monocytes did not confer any protection against lethal sepsis for mice carrying HCN of DEFA1/DEFA3." (PMID 30718392, 2019). "We subjected mice carrying the HCN of DEFA1/DEFA3 genes to the CLP model and treated them three times with the blocking antibody (300 μg, by tail vein injection; immediately, 24 and 48 h after performance of sepsis), or administered an equal amount of mouse IgG or an equal volume of normal saline." (PMID 30718392, 2019).
hyperlipidemia (3 papers, 2016 to 2022). "We recently reported that the PPBP and DEFA1/DEFA3 genes may be feasible synergistic biomarkers for CHD risk in Thai men with hyperlipidemia." (PMID 35734636, 2022). "We recently reported that the PPBP and DEFA1/DEFA3 genes could act as biomarkers for CHD risk in Thai men with hyperlipidemia." (PMID 35734636, 2022). "The present study aimed to determine the values of the PPBP and DEFA1/DEFA3 genes and their encoded proteins as biomarkers of CHD risk in postmenopausal Thai women with hyperlipidemia." (PMID 35734636, 2022). "Based on these data, we suggest that significantly increased expression of both PPBP and DEFA1/DEFA3 and their encoded proteins has the potential to be established as a synergistic predictive biomarker for CHD risk in hyperlipidaemia patients." (PMID 28420383, 2017). "Our results showed that DEFA1/DEFA3 mRNA expression was not significantly different between these groups (p > 0.05), i.e., DEFA1/DEFA3 expression was similar between hyperlipidemia and CHD patients." (PMID 27430968, 2016). "DNA microarray analysis revealed that DEFA1/DEFA3 are expressed in both hyperlipidemia and CHD patients." (PMID 27430968, 2016). "Among eight potential markers, PPBB and DEFA1/DEFA3 were the most strongly correlated with CHD development, and show promise for further application as inflammatory markers to synergistically predict the risk of CHD development in Thai hyperlipidaemia patients." (PMID 28420383, 2017). "Therefore, we suggest that DEFA1/DEFA3 may serve as a biomarker for CHD development in hyperlipidemia patients." (PMID 27430968, 2016). "The results indicate that gene and protein expression levels of PPBP, but not DEFA1/DEFA3, and HNP-1–3, may be feasible biomarkers for assessing CHD risk in postmenopausal Thai women with hyperlipidemia." (PMID 35734636, 2022).
acute myeloid leukemia (2 papers, 2022 to 2025). Acute myeloid leukemia (AML) is a group of neoplasms arising from precursor cells committed to the myeloid cell-line differentiation. "High expression levels of DEFA3 were relevant to a poor prognosis in children with acute myeloid leukemia." (PMID 40612663, 2025). "The mRNA expression levels of DEFA1, DEFA3, and DEFA4 in tumor tissues were generally lower than those in normal tissues but significantly higher in tumor cells of acute myeloid leukemia than those in normal tissues." (PMID 36703795, 2022).
asthma (2 papers, 2022 to 2025). "Most DEGs of this term, including DEFA3, DEFA4, ELANE, and LTF, encode antimicrobial peptides in neutrophils, indicating that the upregulated antimicrobial immune response in the AR-asthma group is mainly mediated by neutrophils." (PMID 36569909, 2022). "Bacterial exacerbations are marked by phagocytic activity, viral exacerbations involve DEFA3 and inflammatory pathways, and unknown etiologies suggest protozoan involvement and possible overlap with asthma–COPD overlap syndrome (ACOS)." (PMID 39859341, 2025).
systemic lupus erythematosus (2 papers, 2007 to 2009). An autoimmune multi-organ disease typically associated with vasculopathy and autoantibody production. "Increase in transcript abundance for genes included in this module may be an indication of an increase in the abundance of immature neutrophils (for example, DEFA1, DEFA3, FALL-39) as was reported earlier in patients with systemic lupus erythematosus." (PMID 19903332, 2009). "On the other hand, DEFA3 but not DEFA1, has been found upregulated in patients with systemic lupus erythematosus, idiopathic thrombocytopenic purpura or rheumatoid arthritis, suggesting that DEFA3 upregulation might be a general feature of autoimmune diseases." (PMID 17214878, 2007).
Allergy (1 paper, 2015). An allergy is an immune response or reaction to substances that are usually not harmful. "We found that the levels of expression of genes involved in allergy development and innate immunity, including those encoding CLC, MS4A3, DEFA3, DEFA4, IL8RA, and IL8RB, were lower in PBMCs from IgG4-RD patients than from healthy controls." (PMID 25973893, 2015). "The expression of genes related to allergy or innate immunity, including CLC, MS4A3, DEFA3, DEFA4, IL8RA and IL8RB, was lower in PBMCs from patients with IgG4-RD than from healthy controls." (PMID 25973893, 2015).
Alzheimer disease (1 paper, 2026). A progressive, neurodegenerative disease characterized by loss of function and death of nerve cells in several areas of the brain leading to loss of cognitive function such as memory and language. "This extended signature includes granule proteins CAMP, CTSG, DEFA3, and MPO secreted from neutrophils and points to olfactomedin 4 (OLFM4) as a new target for the prevention of Alzheimer's disease." (PMID 41316897, 2026). "The signature supports the role of APOE in lipid regulation through apolipoproteins and inflammation and includes, among others, neutrophil secreted granule proteins CAMP, CTSG, DEFA3, and MPO that point to inhibition of OLFM4 as a target for Alzheimer's disease therapeutics." (PMID 41316897, 2026).
autoimmune disease (1 paper, 2007). A disorder resulting from loss of function or tissue destruction of an organ or multiple organs, arising from humoral or cellular immune responses of the individual to their own tissue constituents. "Therefore, the observed differences in DEFA3 absence may partially explain the different population incidences of infectious and/or autoimmune diseases in which DEFA3 plays an important role." (PMID 17214878, 2007).
bladder cancer (1 paper, 2021). "DEFA3 belongs to the α-defensins secreted by neurophils, and the preoperative plasma levels of DEFA3 are positively associated with the progression and pathological stages of bladder cancer." (PMID 34336846, 2021).
chronic lymphocytic leukemia (1 paper, 2025). "Using 3DFunc, IGHV3‐23′s critical role in chronic lymphocytic leukemia is identified and it is found that three pathological SNPs (rs6605578, rs7814783, rs2738144) interact with DEFA3." (PMID 40134047, 2025).
colon cancer (1 paper, 2025). "Functional validation showed that DEFA3 inhibits colon cancer cell migration and proliferation in vitro." (PMID 41009818, 2025).
colorectal cancer (1 paper, 2025). A primary or metastatic malignant neoplasm that affects the colon or rectum. "The upregulation of immune-related genes such as MPO and DEFA3 highlights their potential as biomarkers for the detection of advanced colorectal cancer stages." (PMID 40003985, 2025).
Graves ophthalmopathy (1 paper, 2024). An autoimmune disorder of the EYE, occurring in patients with Graves disease. "The alpha-defensins DEFA1, DEFA1B, and DEFA3 are overexpressed in orbital adipose tissue from patients with Grave’s ophthalmopathy." (PMID 38668354, 2024).